VDAC1 (voltage dependent anion channel 1)
Description:
Non-selective voltage-gated ion channel that mediates the transport of anions and cations through the mitochondrion outer membrane and plasma membrane. The channel at the outer mitochondrial membrane allows diffusion of small hydrophilic molecules; in the plasma membrane it is involved in cell volume regulation and apoptosis. It adopts an open conformation at low or zero membrane potential and a closed conformation at potentials above 30-40 mV. The open state has a weak anion selectivity whereas the closed state is cation-selective. Binds various signaling molecules, including the sphingolipid ceramide, the phospholipid phosphatidylcholine, and the sterols cholesterol and oxysterol. In depolarized mitochondria, acts downstream of PRKN and PINK1 to promote mitophagy or prevent apoptosis; polyubiquitination by PRKN promotes mitophagy, while monoubiquitination by PRKN decreases mitochondrial calcium influx which ultimately inhibits apoptosis. May participate in the formation of the permeability transition pore complex (PTPC) responsible for the release of mitochondrial products that triggers apoptosis. May mediate ATP export from cells. Part of a complex composed of HSPA9, ITPR1 and VDAC1 that regulates mitochondrial calcium-dependent apoptosis by facilitating calcium transport from the ER lumen to the mitochondria intermembrane space thus providing calcium for the downstream calcium channel MCU that directly releases it into mitochondria matrix (By similarity). Mediates cytochrome c efflux. Catalyzes the scrambling of phospholipids across the outer mitochondrial membrane; the mechanism is unrelated to channel activity and is capable of translocating both anionic and zwitterionic phospholipids.
Synonyms: VDAC-1; MGC111064; PORIN
Tractability: Small molecule: a structure with a bound ligand is known; it has a binding pocket of medium quality. Antibody: UniProt places it where antibodies can reach, with high confidence; its Gene Ontology location is reachable by antibodies, with high confidence; UniProt predicts a signal peptide or a membrane-spanning region. PROTAC: UniProt records ubiquitination sites on it; ubiquitination databases record sites on it; its protein half-life has been measured.
Gene: Protein-coding gene on chromosome 5 (133,971,871 to 134,005,360, reverse strand). Ensembl gene ENSG00000213585.
Subcellular location: Mitochondrion outer membrane; Cell membrane; Membrane raft
Pathways (Reactome):
Autophagy: PINK1-PRKN Mediated Mitophagy
Metabolism: Pyruvate metabolism
Metabolism of proteins: Ub-specific processing proteases
Protein localization: Mitochondrial protein import
Transport of small molecules: Mitochondrial calcium ion transport
Gene Ontology:
Molecular function: ceramide binding; cholesterol binding; identical protein binding; phosphatidylcholine binding; protein binding; protein kinase binding; transmembrane transporter binding; voltage-gated monoatomic anion channel activity; voltage-gated monoatomic ion channel activity; oxysterol binding
Biological process: apoptotic process; epithelial cell differentiation; mitochondrial transmembrane transport; monoatomic anion transport; negative regulation of apoptotic process; negative regulation of calcium import into the mitochondrion; positive regulation of mitophagy; positive regulation of type 2 mitophagy; calcium import into the mitochondrion; pyruvate biosynthetic process; regulation of autophagy of mitochondrion; monoatomic anion transmembrane transport; negative regulation of reactive oxygen species metabolic process; regulation of mitophagy; transmembrane transport
Cellular component: extracellular exosome; membrane; membrane raft; mitochondrial membrane; mitochondrial nucleoid; mitochondrial outer membrane; mitochondrial permeability transition pore complex; mitochondrion; nucleus; plasma membrane; pore complex
Genetic constraint (gnomAD): Loss-of-function variants: 9 observed, 29.25 expected, observed/expected ratio (o/e) 0.31, 90% interval 0.19 to 0.54. The upper end of that interval is the gene's LOEUF score, 0.54, which puts it in group 2 of 6, group 1 being the genes least tolerant of losing a copy. Missense variants: 210 observed, 320.85 expected, observed/expected ratio (o/e) 0.65, 90% interval 0.58 to 0.73. Synonymous variants: 119 observed, 127.42 expected, observed/expected ratio (o/e) 0.93, 90% interval 0.8 to 1.09.
Homologues: Orthologues: chimpanzee VDAC1 (100% identical), rabbit VDAC1 (99% identical), mouse Vdac1 (99% identical), rat Vdac1 (99% identical), tropical clawed frog vdac1 (90% identical), zebrafish vdac1 (86% identical), Drosophila melanogaster porin (58% identical), Drosophila melanogaster Porin2 (36% identical), Drosophila melanogaster CG17139 (25% identical), Drosophila melanogaster CG17140 (24% identical). Paralogues in human: VDAC2 (75% identical), VDAC3 (67% identical).
Diseases named in the same sentence as VDAC1 in open-access papers:
VDAC1 is named in the same sentence as 223 diseases in open-access papers, as found by Europe PMC text mining. Sharing a sentence is not in itself a finding about the gene and the disease. The quoted sentences say what the papers report.
breast carcinoma (46 papers, 2011 to 2025). "As a gatekeeper of mitochondria, the voltage‐dependent anion channel 1 (VDAC1) is associated with the development of breast cancer." (PMID 40620061, 2025). "VDAC1 was also significantly overexpressed in breast cancer and the elevated expression of VDAC1 was also associated with poor prognosis in breast cancer." (PMID 37280526, 2023). "As a gatekeeper of mitochondria, the voltage-dependent anion channel 1 (VDAC1) is associated with the development of breast cancer (BC)." (PMID 35729567, 2022). "The main objective of this article was to evaluate the association of voltage-dependent anion channel 1 (VDAC1) with Cytochrome C (Cytc) expression, various clinicopathological features, and prognosis in breast cancer (BC) patients." (PMID 33680287, 2021). "Another study found that the voltage-dependent anion channel 1 (VDAC1) is also linked to the development of resistance to JQ1 in breast cancer." (PMID 34298819, 2021). "Additionally, we discovered that miR-874-3p was downregulated in breast cancer tissues and was negatively linked with the expression of VDAC1." (PMID 36750173, 2023). "Finally, given that, in cancer, the overexpression of HKII and its association with VDAC1 in the mitochondrial membrane of cancer cells inhibits apoptosis, we propose that, in breast cancer cells, the cytotoxic activity of IA is the consequence of its binding to HKII." (PMID 37569780, 2023). "Expression of VDAC1 is conversely associated with Cytc in BC (P = 0.011), especially in triple-negative breast cancer (TNBC) (P = 0.004)." (PMID 33680287, 2021). "miR-874-3p can participate in the migration, invasion, and proliferation of breast cancer cells by targeting voltage-dependent anion channel 1 (VDAC1)." (PMID 38694824, 2024). "By targeting VDAC1, miRNA-874-3p suppresses the migration, invasion, and proliferation of breast cancer cells." (PMID 38807590, 2024). "In our previous studies, we demonstrated that silencing VDAC1 expression using specific siRNA against human VDAC1 and mouse models of lung, glioblastoma, breast cancer, and others inhibited tumor growth and induced reprogrammed metabolism." (PMID 38607066, 2024). "The findings of the Transwell experiment indicated further that VDAC1 overexpression enhances the capacity of breast cancer cells to move and invade." (PMID 36750173, 2023). "For specific examples, VDAC1 was overexpressed in breast cancer but appeared to be low in endometrial cancer tissues." (PMID 37046443, 2023). "Overexpression of VDAC1 significantly boosted the proliferative potential of breast cancer cells compared to the control group, as determined by CCK8." (PMID 36750173, 2023). "Through in vivo and in vitro experiments, we found that VDAC1 can promote the proliferation, migration and invasion of breast cancer cells." (PMID 36750173, 2023). "We detected miR-874-3p and VDAC1 expression in breast cancer cells and tissues in our investigation." (PMID 36750173, 2023). "To explore the reasons for the abnormally high expression of VDAC1 in breast cancer, we predicted the miRNAs that bind to the 3’UTR region of VDAC1 mRNA through a bioinformatics website." (PMID 36750173, 2023). "Malignancies that overexpress mitochondria-bound HK, such as colon, prostate, lymphoma, glioma, gastric adenomas, and breast cancers, demonstrate the important role that VDAC1-bound HK plays in cell bioenergy, growth rate, and survival of cancer cells." (PMID 37046443, 2023). "Our data suggest that mitochondrial metabolism can be exploited by targeting the DYNLT1-Parkin-VDAC1 axis to further improve the ability of metabolic inhibitors to suppress breast cancers with limited treatment options, such as TNBC, in the future." (PMID 37280526, 2023). "VDAC1 was validated as a target gene of miR-874-3p in the breast cancer molecular regulation mechanism, and its molecular regulation mechanism was investigated." (PMID 36750173, 2023).
breast carcinoma (continued). "In summary, this study demonstrates that DYNLT1 promotes mitochondrial metabolism to fuel breast cancer development by inhibiting Parkin-mediated ubiquitination degradation of VDAC1." (PMID 37280526, 2023). "Through bioinformatics, we found that VDAC1 is abnormally highly expressed in breast cancer, and the prognosis of breast cancer patients with high VDAC1 expression is poor." (PMID 36750173, 2023). "Western blotting revealed that VDAC1 protein expression was considerably higher in breast cancer tissues than in surrounding tissues." (PMID 36750173, 2023). "Through analysis, we found that miR-874-3p can regulate the expression of VDAC1, and the expression of miR-874-3p is decreased in breast cancer, resulting in the increase of VDAC1 expression." (PMID 36750173, 2023). "By studying the TCGA database, we discovered that the expression of VDAC1 is elevated in breast cancer patients, and that these patients had a bad prognosis." (PMID 36750173, 2023). "Overexpressed VDAC1 was a prognostic element and was related to immune infiltrates in breast cancer." (PMID 37700273, 2023). "Our data demonstrate that DYNLT1 promotes mitochondrial metabolism to fuel breast cancer development by inhibiting Parkin-mediated ubiquitination degradation of VDAC1." (PMID 37280526, 2023). "Among them, two proteins, such as voltage-dependent anion-selective channel 1 (Vdac1) and Mtdh, gave a significantly low survival rate for patients with breast cancer in the TCGA database." (PMID 36923539, 2023). "We also found VDAC1 S104 phosphorylation raised in various cancers, such as breast cancer, colon cancer, and lung adenocarcinoma." (PMID 35958281, 2022). "Next, we explored the relationship between the expression of HK2 and VDAC1 and the prognosis of breast cancer patients." (PMID 36186902, 2022). "Recently, Bcl-xL has been reported to dampen VDAC1-mediated mitochondrial Ca2+ uptake in breast cancer cells." (PMID 34750538, 2022). "Further bioinformatics analysis revealed that VDAC1 was expressed at a higher level in breast cancer than normal tissues and higher level of VDAC1 predicted poorer survival outcomes in breast cancer patients." (PMID 36186902, 2022). "To explore the effect of lidocaine on VDAC1 expression in breast cancer cells, we analyzed VDAC1 expression after different concentrations of lidocaine cultures by immunofluorescence labeling staining." (PMID 36042412, 2022). "In this study we used clinical data of invasive breast cancer patients, high-throughput gene expression data, and in vitro experiments to investigate the effect of lidocaine on VDAC1 expression in BRCA and its mechanism." (PMID 36042412, 2022). "The protein levels of HK2 and VDAC1 and the effects on the prognosis of breast cancer patients were analyzed based on online databases." (PMID 36186902, 2022). "The expression of VDAC1 protein In breast cancer tissues and adjacent tissues was performed by immunohistochemical staining of paraffin sections." (PMID 36042412, 2022). "Our results showed VDAC1 protein expression and phosphorylation level at the S104 were elevated in breast cancer, colon cancer, lung adenocarcinoma, ovarian cancer, and uterine corpus endometrial carcinoma except for clear cell renal cell carcinoma." (PMID 35958281, 2022). "In this study, we observed that VDAC1 was elevated while Cytc was decreased in breast carcinoma patients compared with benign breast lesions." (PMID 33680287, 2021). "As TNBC showed more progressively malignant manifestation with worse clinical outcomes and is the most insensitive subtype of breast cancer to drug treatment, we next explored the correlation of VDAC1 expression with the prognosis of TNBC." (PMID 33680287, 2021). "In the present study, 219 cases of primary invasive breast cancer tissues were collected, and it was found that VDAC1 protein was primarily located in the membrane of breast cancer cells." (PMID 33680287, 2021).
breast carcinoma (continued). "In case of breast cancer cells the increase of VDAC1 expression was detected for nanosecond protocols EP6, EP7, EP8, and when calcium electroporation was used." (PMID 32111987, 2020). "For breast cancer, it was demonstrated that proapoptotic proteins and voltage-dependent anion channel 1 (VDAC-1) expression were increased after treatment." (PMID 32085381, 2020). "Our results indicate that HKDC1 is located on the mitochondria membrane, interacts with VDAC1, and modulates the permeability transition pore, subsequently modulating glucose uptake in breast cancer cells." (PMID 31058090, 2019). "Breast cancer stem cell (BCSC)-specific markers were highly reduced upon VDAC1 silencing in tumours established from the TNBC MDA-MB-231cell line, including ALDH1, CD133, EPCAM, SOX2 and KLF4." (PMID 30544833, 2018). "Concomitant with the notable decrease in VDAC1 expression levels, the growth of tumours derived from lung or breast cancer or GBM cells was inhibited." (PMID 30544833, 2018). "Despite the critical involvement of VDAC1 in various tumors, little is known of VDAC1 in breast cancer." (PMID 27229534, 2016). "To conclude, these results indicate that MTDH and VDAC1 are potential targets of miR-320a in breast cancer." (PMID 27229534, 2016). "Overexpressed VDAC1 in breast cancer could be served as a novel biomarker for diagnosis and VDAC1 was an independent factor for adverse prognosis prediction." (PMID 40620061, 2025). "Moreover, VDAC1 expression is upregulated in breast carcinoma and downregulated in endometrial carcinoma." (PMID 39201614, 2024). "However, no articles have reported the targeting link between miR-874-3p and VDAC1 and the role of miR-874-3p in breast cancer." (PMID 36750173, 2023). "All of these data demonstrated that VDAC1 can enhance breast cancer malignancy in vitro." (PMID 36750173, 2023). "First, we found that VDAC1 can interact with the E3 ligase Parkin in breast cancer cells." (PMID 37280526, 2023). "VDAC1 is a miR-874-3p target gene, and miR-874-3p inhibits its expression in breast cancer cells." (PMID 36750173, 2023). "Previous research has reported that VDAC1 is a pan-cancer target, which is significantly overexpressed in breast cancer, cervical squamous cell carcinoma, pancreatic cancer, lung adenocarcinoma and melanoma, and the upregulation of VDAC1 is significantly associated with poor prognosis." (PMID 37280526, 2023). "In vitro and in vivo studies demonstrate that VDAC1 promotes breast cancer." (PMID 36750173, 2023). "In addition, Co-IP results showed a significant endogenous interaction between DYNLT1 and VDAC1 in both MCF-7 and MDA-MB-468 breast cancer cells, further suggesting that VDAC1 protein is regulated by DYNLT1." (PMID 37280526, 2023). "Survival analysis of ion channels interacting with EMT-related genes showed KCNN4 (p-value: 0.071), CFTR (p-value: 0.16), KCNJ10 (p-value: 0.17), VDAC1 (p-value: 0.000003) and VDAC2 (p-value: 0.052) the level of expression associated with survival of breast cancer patients." (PMID 35326596, 2022). "Lidocaine may promote apoptosis in breast cancer cells by inhibiting VDAC1 expression, thereby inhibiting breast cancer cell activity." (PMID 36042412, 2022). "Since Ca2+ transfers between the ER and the mitochondria are tightly connected, we speculate that Bcl-xL could inhibit both VDAC1 and IP3Rs in breast cancer cells to promote cancer malignant features." (PMID 34750538, 2022). "Lidocaine may inhibit the activity of breast cancer cells by inhibiting the expression of VDAC1, increasing the apoptosis in breast cancer cells." (PMID 36042412, 2022). "VDAC1 protein was mainly expressed in the membrane of breast cancer cells." (PMID 33680287, 2021). "By the multivariate analysis, we found that overexpression of VDAC1 could be employed as an independent poor prognostic factor in breast cancer, including TNBC, which was intractable in clinical." (PMID 33680287, 2021).